GPLD1 (glycosylphosphatidylinositol specific phospholipase D1)
Description:
Hydrolyzes the inositol phosphate linkage of glycosylphosphatidylinositol (GPI)-anchored membrane proteins, thereby releasing them from the cell surface. Cleaves on the inositol side of the anchor, leaving the phosphate group attached to the membrane. This release of GPI-anchored proteins can modulate diverse biological processes, including the activation of signaling pathways.
Synonyms: PIGPLD1; GPIPLD; GPIPLDM; PIGPLD; PLD
Tractability: Antibody: its Gene Ontology location is reachable by antibodies, with high confidence; UniProt places it where antibodies can reach, with medium confidence; UniProt predicts a signal peptide or a membrane-spanning region.
Gene: Protein-coding gene on chromosome 6 (24,424,565 to 24,495,205, reverse strand). Ensembl gene ENSG00000112293.
Subcellular location: Secreted
Pathways (Reactome):
Metabolism of proteins: Post-translational modification: synthesis of GPI-anchored proteins
Gene Ontology:
Molecular function: glycosylphosphatidylinositol phospholipase D activity; phospholipase D activity; sodium channel regulator activity
Biological process: cell migration involved in sprouting angiogenesis; cellular response to cholesterol; cellular response to insulin stimulus; cellular response to pH; cellular response to triglyceride; cellular response to xenobiotic stimulus; complement receptor mediated signaling pathway; insulin receptor signaling pathway; negative regulation of cell population proliferation; positive regulation of apoptotic process; positive regulation of endothelial cell migration; protein secretion; regulation of cellular response to insulin stimulus; response to glucose; C-terminal protein lipidation; chondrocyte differentiation; hematopoietic stem cell migration; hematopoietic stem cell migration to bone marrow; negative regulation of triglyceride catabolic process; ossification; positive regulation of glucose metabolic process; positive regulation of high-density lipoprotein particle clearance; positive regulation of insulin secretion involved in cellular response to glucose stimulus; positive regulation of triglyceride biosynthetic process; transepithelial transport
Cellular component: cytoplasm; extracellular exosome; extracellular region; lysosomal membrane; extracellular matrix
Genetic constraint (gnomAD): Loss-of-function variants: 31 observed, 50.52 expected, observed/expected ratio (o/e) 0.61, 90% interval 0.46 to 0.83. The upper end of that interval is the gene's LOEUF score, 0.83, which puts it in group 3 of 6, group 1 being the genes least tolerant of losing a copy. Missense variants: 608 observed, 644.69 expected, observed/expected ratio (o/e) 0.94, 90% interval 0.88 to 1.01. Synonymous variants: 250 observed, 262.98 expected, observed/expected ratio (o/e) 0.95, 90% interval 0.86 to 1.06.
Homologues: Orthologues: chimpanzee GPLD1 (99% identical), macaque GPLD1 (94% identical), dog GPLD1 (83% identical), pig GPLD1 (83% identical), guinea pig GPLD1 (80% identical), rat Gpld1 (80% identical), mouse Gpld1 (80% identical), rabbit GPLD1 (78% identical), tropical clawed frog gpld1 (56% identical).
Diseases named in the same sentence as GPLD1 in open-access papers:
GPLD1 is named in the same sentence as 108 diseases in open-access papers, as found by Europe PMC text mining. Sharing a sentence is not in itself a finding about the gene and the disease. The quoted sentences say what the papers report.
breast carcinoma (23 papers, 2010 to 2024). "The risk score of breast cancer prognosis was determined with the following formula: RiskScore = 0.629*ANO6 + 0.147*CELSR3 + 0.381*CLDN7+ 0.273*EPB41L4B-0.357*FAM166B -0.843*GPLD1–0.202*LEF1–0.202*PPARG -0.127*SUSD3." (PMID 34364397, 2021).
Obesity (11 papers, 2016 to 2026). Accumulation of substantial excess body fat. "We investigated whether different PA modes, diseases (obesity, hypertension, and diabetes), and age affect plasma GPLD1 levels using three different study cohorts." (PMID 42224196, 2026). "This presumably has prevented use of GPLD1 protein as biomarker for diabetes or obesity so far." (PMID 33802150, 2021). "Notably, CPN2 (carboxypeptidase N Subunit 2), F5 (coagulation factor V), ECM1 (extracellular matrix protein 1), KNG1 (kininogen 1), FN1 (fibronectin 1), and GPLD1 (glycosylphosphatidylinositol-specific phospholipase D1) were found to be elevated in both human and mouse sEVs under obesity conditions." (PMID 38402239, 2024).
diabetes (10 papers, 2014 to 2026). "GPLD1, the focus attention of our study, is an enzyme abundant in serum, which has been associated with different glucose metabolism status and diabetes." (PMID 32467736, 2020). "We further analyzed the association between serum GPLD1 levels with glycemic parameters and circulating insulin levels because GPLD1 is well-known to be associated with diabetes." (PMID 32467736, 2020). "Glycosylphosphatidylinositol-specific phospholipase D (GPLD1) is responsible for cleaving membrane-associated glycosylphosphatidylinositol (GPI) molecules, which is affected by diabetes." (PMID 32467736, 2020). "Further experiments are required to determine the effects of exercise training on the regulation and function of GPLD1 in diabetes." (PMID 32467736, 2020). "Experimental diabetes significantly increased serum GPLD1 levels (p < 0.001), while exercise training significantly decreased its levels (p < 0.001)." (PMID 32467736, 2020). "Although accumulating studies have been shown a variety of therapeutic mechanisms of exercise training in diabetes, a paucity of knowledge exists regarding the exercise-induced regulation and function of GPLD1 in serum." (PMID 32467736, 2020). "In contrast, accumulating evidence suggests that GPI-PLD (GPLD1) has an important role in insulin signaling and pathogenesis of insulin resistance and diabetes." (PMID 24971987, 2014). "In conclusion age and diabetes affect plasma GPLD1 levels in humans." (PMID 42224196, 2026). "The serum concentration of GPLD1 is directly proportional to total triglyceride, cholesterol, and insulin, implying a pivotal role for GPLD1 in triglyceride metabolism, insulin resistance, and the development of diabetes." (PMID 38085726, 2023). "However, further experiments are required to examine the potential antioxidant and anti-inflammatory roles of exercise training in the regulation of GPLD1 in models of diabetes." (PMID 32467736, 2020). "GPLD1 has a notable role in glucose metabolism and pathogenesis of diabetes." (PMID 32467736, 2020). "The present study revealed that experimental diabetes increased circulating GPLD1 levels in rats." (PMID 32467736, 2020). "In addition, it is possible that by hydrolyzing the GPI anchors of some inflammatory membrane proteins and upregulating macrophage cytokine expression, GPLD1 may play an important role in inflammation and in the pathogenesis of diabetes." (PMID 32467736, 2020). "Interestingly, accumulating evidence has been indicated that GPLD1 levels increased in circulating compartment following the onset of diabetes induction and insulin resistance both in rats and humans, respectively, suggesting its notable association with diabetes-induced impairments." (PMID 32467736, 2020). "Habitual physical activity did not alter plasma GPLD1 levels in individuals with prediabetes or diabetes." (PMID 42224196, 2026). "Elderly with diabetes showed significantly higher GPLD1 levels than non-diabetic subjects." (PMID 42224196, 2026).
Alzheimer disease (9 papers, 2011 to 2026). A progressive, neurodegenerative disease characterized by loss of function and death of nerve cells in several areas of the brain leading to loss of cognitive function such as memory and language. "This study investigated the therapeutic potential of exercise training and the associated role of Glycosylphosphatidylinositol-specific phospholipase D1 (GPLD1) in an experimental Alzheimer’s disease (AD) model." (PMID 42012569, 2026). "Molecular mediators of the benefits of exercise include muscle-derived myokine FNDC5/irisin that prevents neurodegeneration and rescues memory impairment in a model of Alzheimer’s disease, and liver-derived glycosylphosphatidylinositol-specific phospholipase D1 that improves cognition in aged mice." (PMID 33790323, 2021).
Insulin resistance (9 papers, 2014 to 2025). Increased resistance towards insulin, that is, diminished effectiveness of insulin in reducing blood glucose levels. "Other reports have indicated that the relationship between plasma GPLD1 and insulin resistance is controversial." (PMID 27351175, 2016). "In the biological pathway of insulin resistance, the elevated levels of MASP1, THBS1, GPLD1, AAT, HP, RBP4, ZAG, and ApoA-I may be positively correlated with each other, synergistically exacerbating insulin resistance." (PMID 40162315, 2025).
colon carcinoma (6 papers, 2010 to 2025). "GPLD1 has also been implicated in the mechanism underlying the involvement of GPLD1 in carcinoembryonic antigen (CEA) release from human colon cancer cells." (PMID 27351175, 2016).
cognitive decline (4 papers, 2019 to 2022). "In summary, our work suggests that cap‐independent translation of GPLD1 mRNA in the liver leads, indirectly, to changes in brain proteins likely to lead to beneficial cognition effects and the resistance of these long‐lived mice to age‐related cognitive decline." (PMID 35930768, 2022).
type 1 diabetes (4 papers, 2014 to 2021). "This holds even more true for GPLD1 activity, which was only very moderately increased in serum from diabetic and old rats and mice, as well as from type 1 diabetic patients." (PMID 33802150, 2021). "Western blot analysis showed that the relative expression of GPLD1 among the four cohorts [LADA (n = 174), classic type 1 diabetes (n = 156), T2DM (n = 195) and normal controls (n = 166)] was 0.84±0.02, 0.88±0.02, 0.59±0.01, and 0.60±0.01, respectively." (PMID 27351175, 2016). "In line with our finding, several studies have reported that circulating GPLD1 levels increased in patients with type 1 diabetes, STZ-induced diabetic rats, nonobese diabetic mice, STZ-induced diabetic CD-1 mice and high-fructose diet-induced diabetic mice as compared to the controls." (PMID 32467736, 2020).
type 2 diabetes (4 papers, 2016 to 2023). "GPLD1 serves as a biomarker that effectively differentiates latent autoimmune diabetes in adults from type 2 diabetes in the early stage, and it was shown that the circulating GPLD1 concentration in diabetic rats could be restored to normal levels by exercise training." (PMID 35745003, 2022). "Since no research has yet investigated the effect of resistance training with hawthorn extract on the levels of glycemic indices, GPLD1 and GPC-4 in type 2 diabetic rats induced by high fat diet-streptozotocin (HFD -STZ), this study was designed." (PMID 37151681, 2023).
fatty liver (3 papers, 2021 to 2025). "Complete loss of GPLD1 protein in serum upon deletion of the GPLD1 gene in mice was shown to result in improvement of glucose tolerance and hepatic steatosis under a high-fat and high-sucrose diet." (PMID 33802150, 2021).
Hyperglycemia (3 papers, 2018 to 2023). An increased concentration of glucose in the blood. "Nevertheless, studies have shown that GPLD1 serum level can be regulated by various factors such as insulin serum level, hyperglycemia, ROS and inflammation." (PMID 37151681, 2023). "In support of this possibility, it has been reported that the treatment of diabetic mice with insulin corrected the hyperglycemia along with a rapid and complete return of serum GPLD1 activity and liver mRNA." (PMID 32467736, 2020). "However, it has been suggested that serum levels of GPLD1 may be regulated by a number of different hormones or metabolites involving circulating insulin levels, hyperglycemia, oxidative stress, and inflammation." (PMID 32467736, 2020).
viral infections (2 papers, 2015 to 2024). "Collectively, these findings demonstrated that Gpld1 is a positive regulator of IFN-I production, and Gpld1 enhances IFN-I immune response when encountering virus infection." (PMID 38809975, 2024). "Conversely, knockdown of Gpld1 reduced IFN-I production during virus infection." (PMID 38809975, 2024). "Moreover, the primary hepatocytes from Gpld1−/− mice showed more severe virus infection, compared with those from Gpld1+/+ mice." (PMID 38809975, 2024). "S2, C and D), which is consistent with Gpld1-mediated up-regulation of IFN-I production and ISG expression during viral infection." (PMID 38809975, 2024).
bacterial pneumonia (1 paper, 2022). Acute infection of the lung parenchyma caused by bacteria (e.g., Streptococcus pneumoniae, Haemophilus influenzae, Chlamydia pneumoniae, Mycoplasma pneumoniae, and Legionella pneumophila). "APOC3 and GPLD1 are involved in lipid metabolism, which has been shown to be dysregulated in bacterial pneumonia, thereby associated with unfavorable outcomes." (PMID 36812516, 2022).
Cognitive impairment (1 paper, 2021). Abnormal cognition is characterized by deficits in thinking, reasoning, or remembering. "It is notable that overexpression of GPLD1 WT but not a catalytic-dead mutant ameliorates age-related cognitive impairment and enhances adult neurogenesis in aged animals." (PMID 34301723, 2021).
dilated cardiomyopathy (1 paper, 2025). Cardiomyopathy which is characterized by dilation and contractile dysfunction of the left and right ventricles. "In dilated cardiomyopathy (DCM), which is a common cause of HFrEF, PHLD (GPLD1) significantly decreased in DCM patients compared to controls, supporting our findings." (PMID 40375290, 2025).
immune complex disease (1 paper, 2023). "Genes involved in the complement cascade including glycosylphosphatidylinositol-specific phospholipase D1 (GPLD1), carnosine dipeptidase 1 (CNDP1) (in KEGG only), superoxide dismutase 3 (SOD3), and butyrylcholinesterase (BCHE) were also prominent in this immune complex disease." (PMID 37238213, 2023).
Impaired glucose tolerance (1 paper, 2026). An abnormal resistance to glucose, i.e., a reduction in the ability to maintain glucose levels in the blood stream within normal limits following oral or intravenous administration of glucose. "GPLD1 exhibited a positive correlation with age in elderly with normal glucose tolerance, and with BMI in subjects with impaired glucose tolerance." (PMID 42224196, 2026).
insulinoma (1 paper, 2019). "Overexpressing GPLD1 in an insulinoma cell line enhanced glucose-stimulated insulin secretion." (PMID 31369641, 2019).
non-small cell lung carcinoma (1 paper, 2023). A group of at least three distinct histological types of lung cancer, including non-small cell squamous cell carcinoma, adenocarcinoma, and large cell carcinoma. "Targeting GPLD1 has been found to inhibit the proliferation of non-small cell lung cancer cells mediated by p38 MAP kinase Knockdown or silencing of FABP5 has been shown to reduce the proliferation and invasiveness of PC cells in vitro and reduce tumor growth and metastasis in vivo." (PMID 37275878, 2023).
cancer (66 papers, 2008 to 2025). A tumor composed of atypical neoplastic, often pleomorphic cells that invade other tissues. "Compared with normal breast tissues, PIGR, GPLD1, PLA2G5 and CORO1A were down-regulated in cancer tissues, while EIF4EBP1 and LPCAT1 were significantly up-regulated." (PMID 41450825, 2025). "Most of these proteins are recognized as potential prognostic biomarkers in liver (TFRC and GPLD1), renal (IGHG1, PRCP, SAA1/2, and IL1RAP) and digestive (PRSS3) cancers in the Human Protein Atlas database." (PMID 41155404, 2025).
tumor (35 papers, 2010 to 2026). "GPLD1 was found to be downregulated in the tumor group compared to the normal group, indicating it is a low-risk gene." (PMID 40346484, 2025).
infection (19 papers, 2010 to 2025). The state of being infected such as from the introduction of a foreign agent such as serum, vaccine, antigenic substance or organism. "Moreover, Gpld1 deficiency significantly lowered the survival rate of mice in response to infection with either VSV or HSV-1." (PMID 38809975, 2024). "Using fluorescence microscopy, we observed that overexpression of Gpld1 inhibited cellular infection of a vesicular stomatitis virus (VSV) with a green fluorescent protein (GFP) gene, and Gpld1 overexpression inhibited VSV infection in a dose-dependent manner." (PMID 38809975, 2024).
brain disorder (1 paper, 2024). A disease affecting the brain or part of the brain. "It is proposed that the favorable effects of exercise on the CNS can be conferred by the administration of exercise mimetics such as Gpld1 through liver–brain crosstalk, suggesting that Gpld1 has the potential to restore neuronal plasticity and function in brain disorders such as AD." (PMID 38308368, 2024).
GPLD1 also shares sentences with these, for which no sentence is quoted: lung carcinoma (6 papers); abscesses (4); atherosclerosis (4); COVID-19 (4); glioma (4); Hypertension (4); colorectal cancer (3); glioblastoma (3); leukemia (3); neurological diseases (3); nonalcoholic fatty liver disease (3); autoimmune disease (2); cardiovascular disease (2); Cerebral ischemia (2); colitis (2); depression (2); hepatocellular carcinoma (2); lung adenocarcinoma (2); malignant melanoma (2); metabolic disease (2); metabolic syndrome (2); neuroblastoma (2); ovarian carcinoma (2); preeclampsia (2); retinal degeneration (2); Sepsis (2); thrombosis (2); adenocarcinoma (1); age (1); anaplastic carcinoma (1).
A further 55 diseases each share a sentence with GPLD1 in 1 paper.